CDH1 (cadherin 1)
Diseases named in the same sentence as CDH1 in open-access papers (continued):
Sharing a sentence is not in itself a finding about the gene and the disease.
cancer (continued). "However, the strength of our study is that we have among the largest CDH1 germline mutation cohorts with up to nearly 20 years of follow-up data, which may explain our findings of other secondary cancers." (PMID 34073553, 2021). "In particular, a paralog of CDH3 is CDH1, cadherin of the E type, a known growth and invasion suppressor whose loss of function contributes to cancer progression through augmented proliferation, invasion, and/or metastasis, and whose mutations have been correlated with various cancers." (PMID 30485296, 2018). "Furthermore, the analysis of a cancer-associated genetic polymorphism in the CDH1 promoter uncovers a mechanism by which noncoding genetic variants influence epigenetic processes and affect functional elements in promoter–proximal transcripts by altering RNA secondary structure." (PMID 28555645, 2017). "In contrast, loss of Cdh1 was recently shown to bypass the dependency of cancer cells on Cdk4/6, indicating that Cdh1 loss may constitute an exclusion criterion for treatment with the recently developed Cdk4/6 inhibitors, or could be a mechanism of acquired resistance to such drugs." (PMID 26650195, 2016). "Previous studies indicate that both Snail and Slug may contribute to the progression of breast and other types of cancer by the down regulation of E-cadherin (CDH1) and other genes associated with the epithelial phenotype and the up regulation of genes associated with the mesenchymal phenotype." (PMID 26988558, 2016). "One of such regulatory SNPs (rSNPs) is the E-cadherin (CDH1) promoter −160C/A SNP (rs16260) which is known to affect E-cadherin promoter transcription by displacing transcription factor binding and has been extensively scrutinized for its association with several diseases especially malignancies." (PMID 25276428, 2014). "CDH1 (E-Cadherin) is a representative of the classic cadherin family and a calcium-dependent cell-cell adhesion glycoprotein, mutations are correlated with a variety of cancers and loss of function may lead to cancer progression and metastasis." (PMID 16893473, 2006). "Based on the UMAP plot retrieved from the Ovary Cancer sc Database, the plot suggests an inverse spatial expression pattern between CDH1 and DNMT3B in several regions." (PMID 41596471, 2026). "More recently, a pro-metastatic role of CDH1 has also been proposed, attributed to its capacity to enhance cancer cell survival." (PMID 41459333, 2026). "Collectively, we define a new TGFβ1/SMAD/lnc-APUE/E-cadherin axis: TGFβ1 activates lnc-APUE to promote cancer metastasis through Alu element-driven STAU1-mediated CDH1 mRNA decay and subsequent E-cadherin downregulation." (PMID 41632098, 2026). "The epithelial cell-cell adhesion molecule cadherin 1 (CDH1/E‐cadherin) forms the adherens junctions in epithelial cells, and the loss of CDH1 facilitates the migration and invasion of carcinoma cells." (PMID 41459333, 2026). "Snail is known to downregulate CDH1 and upregulate VIM, while XBP1 has been recently linked to EMT and metastasis, impacting cancer progression and therapy outcomes." (PMID 39759848, 2025). "Two of these (cancer cells and LEC1, cancer cells and LEC2) exhibited high expression of cancer cell-associated genes such as KRT19, CDH1, MUC1, and TFF1, suggesting their close interaction with cancer cells." (PMID 41249124, 2025). "Equally, the cadherin switch—downregulation of CDH1 (E-cadherin) and upregulation of CDH2 (N-cadherin)—is a hallmark of EMT that enhances migratory and invasive behavior across cancer types, including NSCLC." (PMID 40787462, 2025). "The presence of solo CDH1 signatures across different cancer types further underscores CDH1’s potential as a marker of epithelial integrity and reduced invasiveness, especially in tumors with a preserved epithelial phenotype." (PMID 41048343, 2025). "This representation clearly shows a strong and significant downregulation of the epithelial marker CDH1 in the primary cancer cell lines analyzed." (PMID 40332096, 2025).
cancer (continued). "Bioinformatics analysis indicated that CTNNB1 and CDH1 are involved in placental development and pregnancy maintenance via cell adhesion and junction processes as well as cancer-related pathways." (PMID 40150405, 2025). "Studies indicate that nearly 100% of asymptomatic CDH1 carriers undergoing PTG have cancer foci identified in their gastric tissue, underscoring the silent nature of the disease and the necessity of surgical intervention." (PMID 40585607, 2025). "CDH1 (E-cadherin) serves as a critical epithelial marker whose loss weakens cell–cell adhesion, thereby facilitating EMT and promoting cancer cell dissemination." (PMID 41266827, 2025). "Mechanistically, F. nucleatum promotes CRC progression via the amyloid-like Fusobacterium adhesin A (FadA), which binds to E-cadherin (CDH1) on cancer cells, leading to Wnt/β‐catenin signaling activation and modulation of inflammatory and oncogenic responses." (PMID 40437288, 2025). "Bioinformatic analysis of Kyoto Encyclopedia of Genes pathways suggested that CTNNB1 and CDH1 are involved in cell adhesion and cancer, with implications for placental development." (PMID 40150405, 2025). "Mutations in E-cadherin encoded by CDH1, an important molecule that maintains the adhesion of epithelial cells, will decrease the adhesion ability of the cells and induce EMT of the cancer cells, enhancing their invasive ability." (PMID 40519309, 2025). "As one example of a TSG repressed by DNA hypermethylation in EBVaGCs, we selected CDH1 encoding the E-cadherin effector of EMT and cancer progression." (PMID 40764753, 2025). "Inhibiting APC/C activity with agents like proTAME, which blocks its activation via CDC20 and CDH1, opens new avenues for disrupting cancer cell proliferation and invasion." (PMID 40136519, 2025). "For example, reduced levels of E-cadherin (CDH1) are associated with increased invasiveness and metastasis in several types of cancer." (PMID 41048343, 2025). "CDH1 genotype contributes to the management of clinical practice recommendations for cancer prevention." (PMID 41154377, 2025). "By using markers of specific clusters, we identified five distinct cell types, including cancer‐associated fibroblasts (CAFs) (COL1A1), endothelial cells (PECAM1), epithelial cells (CDH1), immune cells (PTPRC), and neurons (RELN)." (PMID 40038875, 2025). "Among these, CDH1, CDH2, and CDH3 have been implicated in multiple cancers, yet their specific roles in NSCLC remain inadequately defined." (PMID 40860670, 2025). "ClueGO analysis indicated that 16 of the 48 DEPs were directly related to 17 pathways, with CTNNB1 and CDH1 involved in eight pathways related to cell adhesion and junction formation and seven cancer-related KEGG pathways, respectively." (PMID 40150405, 2025). "This CDH1‐VHL‐HIF1α/AARS2‐R5P/TKTL1 circuit is supported by the observation that low R5P levels and high CDH1 expression correlate with proliferating cancer cells and tissues." (PMID 41020695, 2025). "The results showed that cancer cell marker genes, such as CDH1, EPCAM, FOXA1, and GATA3, were enriched within the spatial domain (sections (−120, −90], (−90, −60], (−60, −30] and (−30, 0])." (PMID 39965034, 2025). "These suggest that cancer signatures, including the Warburg effect and angiogenesis, are intrinsically driven by CDH1." (PMID 41020695, 2025). "CDH1 alterations at both gene and epigenetic levels lead to reduced E-cadherin expression, resulting in decreased cell adhesion and cancer-promoting signals." (PMID 38698370, 2024). "The phosphorylated CDH1 was translocated from the membrane to the cytoplasm, a shift that is critical for understanding its role in cancer progression." (PMID 38698370, 2024).
cancer (continued). "E-cadherin (CDH1) is crucial for epithelial cell adhesion, and its dysfunction contributes to cancer progression." (PMID 38698370, 2024). "In Liu, Kang, and Tang, compelling evidence has been presented regarding the relationship between CDH1 (E-cadherin) and miR-25 in the context of cancer." (PMID 38707537, 2024). "Increased CDH1 expression in cancer cells reduces their ability to undergo epithelial–mesenchymal transition and consequently, their metastatic potential." (PMID 38675711, 2024). "ZEB1 induces EMT during cancer metastasis by transcriptionally repressing CDH1, which encodes E-cadherin." (PMID 39518976, 2024). "EMT plays an important role in the invasion and metastasis of various cancers including ATC, which is associated with upregulation of CDH2/N-cadherin and downregulation of CDH1/E-cadherin." (PMID 38500204, 2024). "The most noticeable familial GC is HDGC, a cancer induced by modifications in the gene coding E-cadherin (CDH1)." (PMID 39335135, 2024). "Reduced CDH1 expression is a hallmark of epithelial-mesenchymal transition (EMT), often associated with cancer progression." (PMID 38698370, 2024). "APC/CCDH1 E3 ligase activity is frequently inhibited in cancer cells, likely due to hyperphosphorylation of CDH1 induced by increased CDKs activity, resulting in decreased APC/CCDH1 activity." (PMID 38622115, 2024). "Since MMPs are involved in the EMT process and CDH1 is usually downregulated in cancer cells, the downregulation of MMPs and upregulation of CDH1 in cells exposed to MnBuOE contribute to the reduction in invasion." (PMID 37568630, 2023). "In contrast, epithelial cadherin (CDH-1) was downregulated in cancer tissues compared with control samples, strongly potentiating the transdifferentiation process in MPM cancer tissue." (PMID 37894370, 2023). "In Caco2 cells, platelet-derived mEVs from CRC-induced TWIST1 (at 4 and 24 h) and VIM (at 4 and 24 h) while downregulating CDH1 (at 24 h) vs. cancer cells cultured alone." (PMID 36672299, 2023). "Loss of CDH1 (E-cadherin) and CTNNB1 expressions resulted in increased cell motility and advanced cancer stages and are associated with EMT, a key event during EC development." (PMID 37313172, 2023). "The CDH1 mRNA and E-cad protein levels are positively correlated, and the CDH1 mRNA levels are positively correlated to cancer patient’s survival." (PMID 37189027, 2023). "Our tool and Cancer-SIGVAR were compared with the ClinGen dataset only for CDH1 and PTEN, since those are the genes where Cancer-SIGVAR follows gene-specific guidelines." (PMID 36916756, 2023). "Downregulation of the CDH1 gene and upregulation of CDH3, CDH2, and VIM in EMT is a hallmark of cancer metastasis." (PMID 37151391, 2023). "In all subtypes, four genes—PIK3CA, RHPN2, CRIPAK, and CDH1, were identified as cancer drivers (ZF10)." (PMID 37454130, 2023).
cancer (continued). "Altogether, and upon data integration, cancer cells arising in patients bearing the CDH1-TANGO6 deletion are likely to present decreased apoptosis, increased proliferation and invasion, and no cell cycle arrest." (PMID 37249750, 2023). "On the other hand, possible functional modulations of cell invasiveness or adhesion have been associated with changes in CDH1 and CDH3 expression in other cancers." (PMID 38003666, 2023). "From our predicted interactions, we found that CDH1+_FOXO3-P- is a known critical functional interaction for cancer progression." (PMID 37972206, 2023). "In several cancers, the silencing of E-cadherin is primarily determined by modified methylation level of CDH1 promoter." (PMID 37046772, 2023). "Thus, while multigene panel sequencing allows for rapid analysis of multiple cancer susceptibility genes, is cost-effective, and leads to incremental genetic findings, it also causes dilemmas for both patients and providers in case of incidental finding of CDH1 mutation." (PMID 37761816, 2023). "One of the principal hallmarks of EMT in cancer is the downregulation of the epithelial-cadherin (E-cadherin) gene (CDH1)." (PMID 37046830, 2023). "In another in vitro study, calcitriol was observed to increase the activity of intercellular adhesion molecules that act as components of adherence and tight junctions, including CDH1 (E-cadherin), occludin, claudin-2 and -12, and ZO-1 and -2 in cancer cells." (PMID 37299554, 2023). "The inclusion of CDH1 in multigene panel testing (in France, HBOC and GI panels) has redefined the cancer risk but it has led to the identification of incidental mutations." (PMID 37761816, 2023). "We also report a new colon signet ring cancer case in a CDH1 carrier, a rare aggressive cancer included in CDH1-related malignancies." (PMID 37761816, 2023). "E-cadherin (CDH1) plays a crucial role in cellular adhesion; however, it is usually downregulated in several types of cancer, facilitating invasive growth." (PMID 37568630, 2023). "Suppression of CDH1 gene expression in cancer cells has been widely reported, particularly in cancer cell line-based studies." (PMID 37189027, 2023). "VPS4A is essential in cancers harboring loss of VPS4B adjacent to SMAD4 on chromosome 18q and VPS4B is required in tumors with co-deletion of VPS4A and CDH1 (E-cadherin) on chromosome 16q." (PMID 37404768, 2023). "In some situations, a reverse process called MET occurs, which involves an increase in CDH1 levels and is performed in cancer metastasis." (PMID 37174083, 2023). "Specifically, CC-1 represented the epithelial-like cancer cell subpopulation expressing Epcam, Cdh1, and Krt7." (PMID 37190324, 2023). "Methylation levels of a 4 gene-panel (RUNX3, p16, RASSF1A, and CDH1) showed 89% sensitivity and 100% specificity for cancer detection." (PMID 36980276, 2023). "While previous studies utilized ovarian and prostate cell lines in vivo, these results demonstrate that patient-derived tumors of many cancer types generate CDH1-positive EVs." (PMID 36470535, 2023). "Both of these cancers feature CDH1 gene deficiency, and synthetic lethality between ROS1 and CDH1 has already been established, providing a potential clinical treatment strategy for patients with these types of cancer." (PMID 37324948, 2023). "Although these functions make CAT and CDH1 intriguing examples of genes that have potentially evolved to enhance bat cancer resistance, previous studies have also found a signal for selection in CAT and CDH1 in other mammals." (PMID 37728212, 2023). "Later, allele‐specific primers (both wild type and mutant) were applied and confirmed the presence of selected nsSNP (rs34466743) from the CDH1 gene in blood samples of cancer patients." (PMID 37867380, 2023).
cancer (continued). "CDH1 was downregulated in cancer tissues at both the RNA and protein levels in the CPTAC and Chinese Fudan cohort which detecting by proteome sequencing, and TMA tissues." (PMID 37201027, 2023). "It is worth mentioning that CDH1 can promote the invasiveness and progression of tumors in advanced stages of cancer." (PMID 37174083, 2023). "Among the 9 types of commonly occurring carcinomas analyzed, CDH1 mRNA levels in 6 of them (67%) were upregulated, 2 of them (22%) were unchanged, and only one of them (11%) was downregulated compared to corresponding normal tissues." (PMID 37189027, 2023). "CDH1 mRNA levels were strongly positively correlated with E-cad protein levels for eight of the nine lineages of carcinoma cell lines." (PMID 37189027, 2023). "Consistent with CDH1 mRNA expression in most carcinoma tissues and carcinoma cell lines, E-cad protein was either significantly upregulated or remained unchanged in most carcinoma tissues compared to corresponding normal tissue." (PMID 37189027, 2023). "The relationship between the levels of CDH1 mRNA and E-cad protein in the carcinoma cell lines from nine different lineages stored on DepMap portal was analyzed using Pearson correlation analysis and Spearman correlation analysis." (PMID 37189027, 2023). "Overall, these results demonstrate that higher levels of CDH1 mRNA expression are correlated with better survival of carcinoma patients." (PMID 37189027, 2023). "We then assessed CDH1 mRNA levels in different subtypes or stages of carcinomas in which CDH1 mRNA was upregulated or unchanged." (PMID 37189027, 2023). "On the other hand, genes related to cancer progression (Snai1 and Cdh1) were down regulated in tumors from immunized mice." (PMID 36366425, 2022). "We first compared the mRNA levels of CDH1 in 21 types of cancers with their normal counterparts by using TIMER2.0 database." (PMID 35784532, 2022). "In cancer, genetic and epigenetic alterations in the E-cadherin gene (CDH1) or aberrant protein expression are frequent and result in loss of cell–cell adhesion, increased cell invasion and metastasis." (PMID 34486077, 2022). "For example, neural (N)-cadherin is usually expressed by mesenchymal, neural, endothelial, and poorly differentiated cancer cells, whereas epithelial (E)-cadherin (CDH1) is expressed by epithelial cells and well-differentiated carcinomas." (PMID 35309924, 2022). "The mRNA levels of 14‐3‐3σ and Kaiso target gene CDH1 showed highly significant positive correlations in both human normal tissues and cancer cell lines by bioinformatics analyses." (PMID 35851744, 2022). "Previous studies have reported sporadic cases of multiple cancer types with high DNA methylation levels at the CDH1 promoter, suggesting epigenetic silencing as an alternative mechanism for the downregulation of CDH1." (PMID 35053458, 2022). "The silencing of the E-cadherin encoding gene, CDH1, is mediated by the EMT-promoting transcription factors ZEB1 and Snail, two regulators that are overexpressed in many cancers, and which act jointly to repress both CDH1 and LARGE2 mRNAs." (PMID 36494657, 2022). "Meanwhile, the CDH1 promoter exhibited hypermethylation in a variety of cancers, further reducing CDH1 expression." (PMID 35656554, 2022). "CDC20, an APC activator and substrate, is often overexpressed in cancer cells, while impairment of CDH1 leads to genome instability and cancer development." (PMID 36077749, 2022). "As observed in protein network analysis, both proteins interact with CDH1, a hallmark of EMT in cancers." (PMID 36211450, 2022). "As a cancer suppressor gene coding for E-cadherin and a type of calcium-dependent cell adhesion protein, CDH1 plays a role in regulating cell adhesion, proliferation, and migration." (PMID 35785160, 2022).